SLITRK1 (SLIT and NTRK like family member 1)
Description:
It is involved in synaptogenesis and promotes excitatory synapse differentiation. Enhances neuronal dendrite outgrowth.
Synonyms: KIAA1910; LRRC12; TTM
Tractability: Antibody: UniProt places it where antibodies can reach, with high confidence; its Gene Ontology location is reachable by antibodies, with high confidence; UniProt predicts a signal peptide or a membrane-spanning region. PROTAC: its protein half-life has been measured.
Gene: Protein-coding gene on chromosome 13 (83,877,205 to 83,882,474, reverse strand). Ensembl gene ENSG00000178235.
Subcellular location: Membrane; Secreted; Synapse
Pathways (Reactome):
Neuronal System: Receptor-type tyrosine-protein phosphatases
Gene Ontology:
Molecular function: protein binding
Biological process: positive regulation of axonogenesis; regulation of presynapse assembly; synapse assembly; synaptic membrane adhesion; axonogenesis; positive regulation of synapse assembly; regulation of synapse organization
Cellular component: extracellular region; GABA-ergic synapse; glutamatergic synapse; plasma membrane; postsynaptic density membrane; synapse; membrane; postsynaptic membrane; varicosity
Genetic constraint (gnomAD): Loss-of-function variants: 10 observed, 45.87 expected, observed/expected ratio (o/e) 0.22, 90% interval 0.13 to 0.37. The upper end of that interval is the gene's LOEUF score, 0.37, which puts it in group 1 of 6, group 1 being the genes least tolerant of losing a copy. Missense variants: 778 observed, 906.63 expected, observed/expected ratio (o/e) 0.86, 90% interval 0.81 to 0.91. Synonymous variants: 389 observed, 394.95 expected, observed/expected ratio (o/e) 0.98, 90% interval 0.91 to 1.07.
Homologues: Orthologues: pig SLITRK1 (99% identical), dog SLITRK1 (99% identical), guinea pig SLITRK1 (99% identical), rabbit SLITRK1 (98% identical), mouse Slitrk1 (98% identical), rat Slitrk1 (97% identical), tropical clawed frog slitrk1 (84% identical), chimpanzee SLITRK1 (81% identical). Paralogues in human: SLITRK2 (43% identical), SLITRK5 (41% identical), SLITRK4 (40% identical), SLITRK3 (38% identical), SLITRK6 (38% identical), SLIT3 (19% identical), SLIT2 (18% identical), SLIT1 (18% identical), TLR9 (16% identical), LINGO1 (15% identical), GP5 (14% identical), LRRC70 (14% identical), and 13 more.
Diseases named in the same sentence as SLITRK1 in open-access papers:
SLITRK1 is named in the same sentence as 22 diseases in open-access papers, as found by Europe PMC text mining. Sharing a sentence is not in itself a finding about the gene and the disease. The quoted sentences say what the papers report.
Tourette syndrome (23 papers, 2009 to 2025). A neurologic disorder caused by defective metabolism of the neurotransmitters in the brain. "Variants located in these regions were found to be damaging in Tourette’s syndrome (SLITRK1) and Phosphoglycerate kinase 1 deficiency (PGK1); however, these events are certainly rare and supporting evidence regarding their pathogenicity is hard to gather." (PMID 36084042, 2023). "The SLITRK1 gene is located in the 13q31.1 region and is associated with Gilles de la Tourette's syndrome (OMIM-137580)." (PMID 34980106, 2022). "Several rare variants of SLITRK1 have been identified and implicated in the pathogenesis of Tourette’s syndrome, trichotillomania, and obsessive–compulsive disorder, which can be collectively referred to as obsessive–compulsive-spectrum disorders." (PMID 36683853, 2022). "Variants in SLITRK1 gene are associated with human psychiatric disorders such as Tourette's syndrome and OCD." (PMID 34368281, 2021). "PhenPathTOOL correctly recognizes that the concomitance of phenotypes points to the Tourette syndrome, and to two genes (SLITRK1, HDC) that are associated with the disease." (PMID 31307376, 2019). "For example, Slitrk1 has been postulated to be causative for Tourette syndrome, although subsequent studies have questioned the validity of conclusions reached by these earlier studies." (PMID 27812321, 2016). "Associations to SLITRK1 have also been reported for Tourette’s Syndrome and cyclothymic temperament in bipolar disorder." (PMID 23326512, 2013). "Variants in the binding site for miR-189 in the 3' UTR region of the SLITRK1 gene are associated with Tourette's syndrome." (PMID 20507594, 2010). "It must be underlined, however, that the involvement of SLITRK1 in Tourette's syndrome has been subsequently questioned by other reports." (PMID 19889204, 2009). "Previous studies have shown that mutations in SLITRK1 are involved in Tourette syndrome." (PMID 35456478, 2022). "Patients carrying SLITRK1 variant alleles have known to exhibit Tourette syndrome." (PMID 31097624, 2019). "Among those mutations we found through an exhaustive literature review, there is an ancestral S330A mutation of SLITRK1 that may be involved in obsessive-compulsive disorders like Tourette’s Syndrome." (PMID 29045412, 2017). "The SLITRK1 gene encodes a developmentally regulated stimulator of neurite outgrowth and previous studies have implicated rare variants in this gene in disorders in the OC spectrum, specifically Tourette syndrome (TS) and trichotillomania (TTM)." (PMID 23990902, 2013). "Indeed, among the putative MEs we identified are genes implicated in hypothyroidism (PAX8), and Tourette's syndrome (SLITRK1)." (PMID 21203497, 2010). "Interestingly, SLITRK1 is primarily associated with the nervous system, including its involvement in the pathogenesis of Tourette’s syndrome through cholinergic interneurons in mice, as well as its role in mediating neuropsychiatric behaviors related to chronic neuropathic pain." (PMID 40372036, 2025). "Slitrk1 is a Tourette’s disorder candidate gene and Slitrk5 mouse mutants have obsessive compulsive-like behaviors." (PMID 34879283, 2021). "SLITRK1 had been found to be related to a genetic nervous disorder called Tourette’s syndrome." (PMID 36980855, 2023). "Mutations in the SLITRK1 gene have been reported to be involved in Tourette Syndrome (TS; OMIM No# 137580)." (PMID 35456478, 2022). "Given that Slitrk1 is expressed during the development of corticostriatal pathways, a potential role for Slitrk1 in the regulation of corticostriatal connectivity and its possible involvement in Tourette syndrome warrants further investigation." (PMID 31097624, 2019). "Tourette syndrome was the first neuropsychiatric disease etiologically linked to miRNAs, when TS patients were reported to have a mutation in the binding site of miR-189 at the 3’ UTR of the SLITRK1 gene." (PMID 26205656, 2015).
Tourette syndrome (continued). "SLITRK1, the most widely studied gene in Tourette Syndrome, did not yield a positive finding in this study." (PMID 32922348, 2020). "However, the core symptoms of Tourette syndrome and trichotillomania, such as self-grooming, were not reported in Slitrk1-KO mice." (PMID 27812321, 2016).
Anxiety (6 papers, 2013 to 2024). Intense feelings of nervousness, tension, or panic often arise in response to interpersonal stresses. "Taken together, the neonatal body weight loss, neonatal vocalization abnormalities, and anxiety-like and depression-like behaviors in the adolescent and adult stages feature neurodevelopmental phenotypes in Slitrk1 KO mice." (PMID 36683853, 2022). "Slitrk1-deficient mice show neonatal dysregulation of the noradrenergic system, and later, anxiety-like behaviors that can be attenuated by an alpha 2 noradrenergic receptor agonist." (PMID 36683853, 2022). "Furthermore, clonidine attenuated anxiety-like behavior in Slitrk1-deficient mice." (PMID 36085162, 2022). "Slitrk1-KO mice exhibit anxiety-like behaviors due to neonatal dysregulation of the noradrenergic system, which can be reduced by an alpha-2 noradrenergic receptor agonist." (PMID 39334827, 2024). "SLITRK1 knock-out mice showed increased anxiety-like behaviors and abnormal noradrenergic activity, and also had higher levels of norepinephrine and metabolite 3-methoxy-4-hydroxyphenylglycol." (PMID 36980855, 2023). "Remarkably, Slitrk1-knockout (KO) mice exhibit elevated anxiety-like behaviors that are attributable to increased norepinephrine levels, and administration of the centrally acting adrenergic agonist clonidine has been shown to normalize these behaviors." (PMID 27812321, 2016). "Thus, Slitrk1 is a potential candidate genetic linkage between the neonatal noradrenergic signaling and the pathophysiology of neuropsychiatric disorders involving anxiety-like or depression-like behaviors." (PMID 36683853, 2022). "Furthermore, SLITRK1 could be involved in the pathogenesis of other neuropsychiatric disorders involving depression and anxiety." (PMID 36085162, 2022).
depression (3 papers, 2013 to 2022). "Additionally, we note a potential relationship between the SLITRK1-T418S variant in depression as four of the five individuals with the T418S missense mutation (including the non-OC spectrum individual) have a diagnosis of MDD and the remaining individual has a history of attempted suicide." (PMID 23990902, 2013).
obsessive-compulsive disorder (3 papers, 2013 to 2022). A disorder characterized by the presence of persistent and recurrent irrational thoughts (obsessions), resulting in marked anxiety and repetitive excessive behaviors (compulsions) as a way to try to decrease that anxiety. "Consistent with the increased obsessive-compulsive disorder prevalence in males in childhood, the prefrontal cortex of male Slitrk1-KO newborns show increased noradrenaline levels, and serotonergic varicosity size." (PMID 36085162, 2022).
schizophrenia (3 papers, 2016 to 2022). A major psychotic disorder characterized by abnormalities in the perception or expression of reality. "However, many missense mutations have been identified in SLITRK1 from not only disease cases, but also control subjects upon whole exome sequencing studies for bipolar disorder, schizophrenia, and epilepsy." (PMID 36683853, 2022). "Furthermore, a genome-wide association study identified a single nucleotide polymorphism ca 780 kb upstream of SLITRK1, associated with schizophrenia." (PMID 36683853, 2022). "Loss of SLITRK1 results in altered behaviour and in increased noradrenergic projections in OCD-related neural circuits, suggesting that differences in noradrenergic signaling may contribute to numerous neurodevelopmental disorders, including OCD, schizophrenia, and bipolar disorder." (PMID 36085162, 2022).
asthma (1 paper, 2025). "SLITRK1 is associated with neurite development and synaptogenesis, and increased CCL11 expression can exacerbate asthma." (PMID 41472112, 2025).
atrial fibrillation (1 paper, 2024). A disorder characterized by an electrocardiographic finding of a supraventricular arrhythmia characterized by the replacement of consistent P waves by rapid oscillations or fibrillatory waves that vary in size, shape and timing and are accompanied by an irregular ventricular response. "These proteins tended be associated with higher risk of incident atrial fibrillation (except for two proteins associated with lower HF risk, SLITRK1 and PTPRD) and variable associations with incident CKD and/or diabetes." (PMID 38225249, 2024).
epilepsy (1 paper, 2024). A brain disorder characterized by episodes of abnormally increased neuronal discharge resulting in transient episodes of sensory or motor neurological dysfunction, or psychic dysfunction. "Conversely, an increase in the expression levels of SLIT and NTRK-like family, member 1 (Slitrk1), TYRO3 protein tyrosine kinase 3 (Tyro3), epilepsy, progressive myoclonic epilepsy, type 2 gene alpha (Epm2a), fucosyl-transferase 9 (Fut9), immunoglobulin superfamily, member 9B (Igsf9b) was observed." (PMID 38535448, 2024).
Obesity (1 paper, 2025). Accumulation of substantial excess body fat. "It identified three plasma proteins (FLT1, GAP43, and SLITRK1) that were significantly associated with obesity and showed a causal relationship." (PMID 40372036, 2025). "The findings of the study revealed that three plasma proteins (FLT1, GAP43, and SLITRK1) were significantly associated with the risk of obesity and showed a causal relationship." (PMID 40372036, 2025). "The study investigated the causal relationship between three plasma proteins (FLT1, GAP43, and SLITRK1) and obesity, finding that they have a protective effect against obesity risk." (PMID 40372036, 2025). "In summary, the study identified three plasma proteins, FLT1, GAP43, and SLITRK1, as having a protective effect against obesity risk." (PMID 40372036, 2025). "FLT1, GAP43, and SLITRK1 remained significant under the MR hypothesis and were identified as having a cause-and-effect relationship with obesity according to the IVW method." (PMID 40372036, 2025). "FLT1 exhibited a causal relationship with obesity (OR: 0.939, 95% CI: 0.901–0.978, P = 0.002), GAP43 showed a causal relationship with obesity (OR: 0.897, 95% CI: 0.806–0.998, P = 0.046), and SLITRK1 was causally linked to obesity (OR: 0.855, 95% CI: 0.736–0.994, P = 0.041)." (PMID 40372036, 2025). "We found that SLITRK1 plays a pivotal role in reducing the risk of obesity." (PMID 40372036, 2025). "Fms-related receptor tyrosine kinase 1 (FLT1), growth-associated protein 43 (GAP43), and SLIT and NTRK-like family member 1 (SLITRK1) plasma proteins had protective effects against obesity." (PMID 40372036, 2025). "By analyzing genes associated with SNPs causally linked to obesity, gut microbiota, and metabolites, we found that FLT1, GAP43, and SLITRK1 proteins potentially reduce the risk of obesity." (PMID 40372036, 2025). "Particularly, the findings revealed a previously unknown role for SLITRK1 in obesity prevention, expanding our understanding of the molecular mechanisms underlying this complex metabolic disorder and shedding light on potential targets for therapeutic interventions against obesity." (PMID 40372036, 2025).
tic disorder (1 paper, 2025). Disorders characterized by recurrent TICS that may interfere with speech and other activities. "Thus, the SLITRK1 gene, involved in synapse maturation, has been considered a candidate for the development of OCD, especially in cases of tic disorder." (PMID 40943498, 2025).
cancer (2 papers, 2016 to 2022). A tumor composed of atypical neoplastic, often pleomorphic cells that invade other tissues. "Many of these other potential enhancer-hijacking targets do not have well-established roles in cancer pathogenesis, however, we did notice a number of genes involved in cell adhesion (ALCAM, NCAM2, CADM2, and CDH9) and 2 SLIT and NTRK like family members (SLITRK1, SLITRK6)." (PMID 35538064, 2022).
SLITRK1 also shares sentences with these, for which no sentence is quoted: trichotillomania (4 papers); bipolar disorder (2); autism (1); diabetes (1); hypothyroidism (1); intrauterine growth restriction (1); male infertility (1); metabolic disorder (1); myoclonic epilepsy (1); neurodevelopmental disorder (1); psychiatric disorder (1).